RNU6-434P (RNA, U6 small nuclear 434, pseudogene)
Gene: Small nuclear RNA gene on chromosome X (54,343,546 to 54,343,652, forward strand). Ensembl gene ENSG00000207104.
Homologues: Orthologues: chimpanzee U6 (98% identical), pig U6 (81% identical). Paralogues in human: RNU6-1316P (94% identical), RNU6-20P (94% identical), RNU6-35P (94% identical), RNU6-1145P (93% identical), RNU6-16P (93% identical), RNU6-25P (93% identical), RNU6-29P (93% identical), RNU6-38P (93% identical), RNU6-393P (93% identical), RNU6-46P (93% identical), RNU6-1 (93% identical), RNU6-144P (93% identical), and 1286 more.